VPS35 (VPS35 retromer complex component)
Description:
Acts as a component of the retromer cargo-selective complex (CSC). The CSC is believed to be the core functional component of retromer or respective retromer complex variants acting to prevent missorting of selected transmembrane cargo proteins into the lysosomal degradation pathway. The recruitment of the CSC to the endosomal membrane involves RAB7A and SNX3. The CSC seems to associate with the cytoplasmic domain of cargo proteins predominantly via VPS35; however, these interactions seem to be of low affinity and retromer SNX proteins may also contribute to cargo selectivity thus questioning the classical function of the CSC. The SNX-BAR retromer mediates retrograde transport of cargo proteins from endosomes to the trans-Golgi network (TGN) and is involved in endosome-to-plasma membrane transport for cargo protein recycling. The SNX3-retromer mediates the retrograde endosome-to-TGN transport of WLS distinct from the SNX-BAR retromer pathway. The SNX27-retromer is believed to be involved in endosome-to-plasma membrane trafficking and recycling of a broad spectrum of cargo proteins. The CSC seems to act as recruitment hub for other proteins, such as the WASH complex and TBC1D5 (Probable). Required for retrograde transport of lysosomal enzyme receptor IGF2R and SLC11A2. Required to regulate transcytosis of the polymeric immunoglobulin receptor (pIgR-pIgA). Required for endosomal localization of WASHC2C. Mediates the association of the CSC with the WASH complex via WASHC2. Required for the endosomal localization of TBC1D5. (Microbial infection) The heterotrimeric retromer cargo-selective complex (CSC) mediates the exit of human papillomavirus from the early endosome and the delivery to the Golgi apparatus.
Synonyms: MEM3; FLJ10752; PARK17
Tractability: Small molecule: a structure with a bound ligand is known. Antibody: UniProt places it where antibodies can reach, with medium confidence. PROTAC: ubiquitination databases record sites on it; its protein half-life has been measured.
Gene: Protein-coding gene on chromosome 16 (46,656,132 to 46,689,518, reverse strand). Ensembl gene ENSG00000069329.
Subcellular location: Cytoplasm; Membrane; Endosome; Early endosome; Late endosome
Subcellular location (Human Protein Atlas): Endosomes; Lysosomes
Pathways (Reactome):
Signal Transduction: WNT ligand biogenesis and trafficking
Gene Ontology:
Molecular function: D1 dopamine receptor binding; protein binding; cargo adaptor activity
Biological process: endocytic recycling; mitochondrial fragmentation involved in apoptotic process; mitochondrion to lysosome vesicle-mediated transport; negative regulation of inflammatory response; negative regulation of late endosome to lysosome transport; neurotransmitter receptor transport, endosome to plasma membrane; positive regulation of dopamine receptor signaling pathway; positive regulation of gene expression; positive regulation of mitochondrial fission; positive regulation of protein catabolic process; positive regulation of protein localization to cell periphery; protein localization to endosome; regulation of dendritic spine maintenance; regulation of mitochondrion organization; regulation of protein metabolic process; regulation of protein stability; regulation of terminal button organization; retrograde transport, endosome to Golgi; transcytosis; endosome to plasma membrane protein transport; regulation of macroautophagy; regulation of presynapse assembly; Wnt signaling pathway; lysosome organization; modulation of chemical synaptic transmission; and 20 more
Cellular component: cytosol; early endosome; endosome; endosome membrane; extracellular exosome; lysosomal membrane; mitochondrion; mitochondrion-derived vesicle; retromer complex; retromer, cargo-selective complex; tubular endosome; cytoplasm; dopaminergic synapse; glutamatergic synapse; late endosome; membrane; neuron projection; neuronal cell body; perinuclear region of cytoplasm; postsynapse; postsynaptic density; presynapse; synapse
Genetic constraint (gnomAD): Loss-of-function variants: 21 observed, 94.36 expected, observed/expected ratio (o/e) 0.22, 90% interval 0.16 to 0.32. The synonymous counts are far from expectation, so gnomAD's model fits this gene poorly and the ratio says little. Missense variants: 539 observed, 953.61 expected, observed/expected ratio (o/e) 0.57, 90% interval 0.53 to 0.61. Synonymous variants: 260 observed, 320.41 expected, observed/expected ratio (o/e) 0.81, 90% interval 0.73 to 0.9.
Gene-disease validity (ClinGen):
ClinGen rates the evidence that VPS35 causes each of these diseases.
Parkinson disease (autosomal dominant): Definitive. A progressive degenerative disorder of the central nervous system characterized by loss of dopamine producing neurons in the substantia nigra and the presence of Lewy bodies in the substantia nigra and locus coeruleus.
Homologues: Orthologues: chimpanzee VPS35 (100% identical), macaque VPS35 (99% identical), rabbit VPS35 (99% identical), guinea pig VPS35 (99% identical), mouse Vps35 (99% identical), rat Vps35 (99% identical), pig VPS35 (95% identical), tropical clawed frog vps35 (95% identical), zebrafish vps35 (94% identical), dog VPS35 (88% identical), Drosophila melanogaster Vps35 (61% identical), Caenorhabditis elegans vps-35 (48% identical).
Diseases named in the same sentence as VPS35 in open-access papers:
VPS35 is named in the same sentence as 104 diseases in open-access papers, as found by Europe PMC text mining. Sharing a sentence is not in itself a finding about the gene and the disease. The quoted sentences say what the papers report.
Parkinson disease (125 papers, 2012 to 2026). "Pathogenic mutations in other Parkinson’s disease genes, including Rab32 and VPS35, also enhance LRRK2 signaling, underscoring the importance of understanding how upstream cellular processes regulate LRRK2 activation." (PMID 41332754, 2025). "Most notably, the D620N mutation in the VPS35 protein is causative of late-onset Parkinson’s disease in an autosomal-dominant manner." (PMID 40082954, 2025). "Candidates for engaging these pathways in the context of Parkinson’s disease pathogenesis include risk genes such as Rab32 and VPS35 that are known to activate LRRK2 and VPS13C that promotes the repair of damaged lysosomes." (PMID 41332754, 2025). "The p.D620N mutation in VPS35 causes an autosomal dominant form of Parkinson's disease via mechanisms that are poorly understood." (PMID 41164908, 2025). "In another study, the authors investigated the role of the VPS35 p.Asp620Asn mutation, linked to a familial form of Parkinson’s disease, termed PARK17 (OMIM 614203)." (PMID 39273694, 2024). "The VPS35 component of the retromer complex transports select endosomal cargo proteins between endosomal compartments and the Golgi and has been linked to Parkinson’s as well as Alzheimer’s diseases." (PMID 38091401, 2023). "Reports have demonstrated that DA release is dysfunctional in models carrying Parkinson’s disease-associated mutations in Vps35." (PMID 36864664, 2023). "VPS35 (D620N) mutations are associated with Parkinson’s disease (PD) phenotypes, dopaminergic neuron loss, and hippocampal Tau accumulation." (PMID 34370162, 2022). "VPS35, which has been extensively linked to neurological diseases such as Parkinson’s and Alzheimer’s disease, appears as a regulator of mtDNA quality control necessary to maintain mitochondrial intactness." (PMID 36344526, 2022). "Dysfunction of the VPS35 retromer complex is a risk factor for Parkinson’s disease and Alzheimer’s disease." (PMID 36378718, 2022). "We have recently described D620N VPS35 knock-in mice that develop robust age-related nigral dopaminergic neurodegeneration, a key hallmark of Parkinson’s disease, as well as widespread axonal damage and tau-positive neuropathology." (PMID 34704029, 2021). "In particular, mutations associated with Parkinson’s disease have been found in a close endosomal interactor of the WASH complex – the retromer protein VPS35 (VPS35D620N and VPS35R524W) – and have been linked to pathological α-synuclein aggregation in vitro." (PMID 33749590, 2021). "Here, we study the basic neurobiology of VPS35 and Parkinson’s disease mutation effects in the D620N knock-in mouse and the effect of leucine-rich repeat kinase 2 (LRRK2) inhibition on synaptic phenotypes." (PMID 34530877, 2021). "Loci associated with rare monogenic forms of Parkinson’s disease, or more complex disorders with a prominent component of parkinsonism, also encode proteins involved in vesicle trafficking: VPS35, ATP13A2, PLA2G6, DNAJC6, SYNJ1, and VPS13C." (PMID 33556113, 2021). "Other members of the vacuolar protein sorting (Vps) family of proteins have been linked to more common neurodegenerative disorders such as Parkinson’s disease (PD) (Vps35 and Vps13c) and frontotemporal dementia (Vps4B)." (PMID 33941276, 2021). "The discovery of dominantly-inherited, late-onset Parkinsonism has recently been linked to a missense mutation in VPS35 which implicates retromer dysfunction in the pathogenesis of PD." (PMID 33800548, 2021). "Since familial VPS35 mutations are linked to Parkinson’s disease and reduced VPS35 levels are associated with certain dementias, we initially focused on the impact of neuronal VPS35 depletion in the brains of mice at P12." (PMID 34704029, 2021). "Other research has revealed that other components genetically linked to Parkinson's disease including Rab29 and VPS35 also regulate phosphorylation of Rab proteins via LRRK2." (PMID 33459343, 2021).
Parkinson disease (continued). "The Parkinson's causing VPS35[D620N] mutation markedly enhances LRRK2-mediated Rab protein phosphorylation." (PMID 33459343, 2021). "We exploit this assay to demonstrate that in Parkinson's patients with VPS35[D620N] mutations, phosphorylation of multiple Rab proteins (Rab1, Rab3, Rab8, Rab10 and Rab43) is elevated." (PMID 33367571, 2021). "Our study suggests that the Parkinson’s disease-causative D620N mutation in Vps35 impedes Tetherin going back onto cell surfaces and facilitates the spread of HSV-1." (PMID 33800686, 2021). "A heterozygous Asp620Asn (D620N) missense mutation in the VPS35 gene causes a late-onset, autosomal dominant form of Parkinson’s disease that is clinically similar to sporadic Parkinson’s disease." (PMID 34704029, 2021). "For example, a mutation in VPS35, causes late-onset Parkinson’s disease, and microarray studies have implicated the retromer complex in Alzheimer’s disease." (PMID 33374212, 2020). "Although implicated in both Parkinson’s and Alzheimer’s disease, our understanding of retromer function in the adult brain remains limited, in part because Vps35 and Vps26 are essential for development." (PMID 32286230, 2020). "The oldest selection time we predict (2,922 generations or 84,738 years, with a generation time of 29 years) occurred on VPS35, a gene on which mutations are associated with Parkinson’s Disease." (PMID 32853200, 2020). "In support of this, the pathophysiology of Parkinson’s disease is linked with a mutation in the retromer subunit VPS35." (PMID 33374212, 2020). "Overall frequencies of LRRK2, SNCA, and VPS35 mutations according to index case ethnicity, family history of Parkinson's disease and age at onset." (PMID 32849182, 2020). "MDV trafficking has been implicated in Parkinson’s and Alzheimer’s disease through association of the vps35 protein, which is mutated in the diseases and involved in MDVs transport." (PMID 32587311, 2020). "Pathologically, VPS35-deficiency is believed to increase the risk of neurodegenerative diseases, including Alzheimer’s disease (AD) and Parkinson’s disease (PD)." (PMID 31771656, 2019). "This mutation had striking different functional consequences than the previously reported Parkinson disease-causing VPS35 variant, even though both affected amino acids are located close to each other in the protein sequence." (PMID 30478624, 2019). "It has been shown that the Parkinson's disease (PD)-causing mutation in VPS35 (D620N) causes a reduction in association of the retromer CSC with the WASH complex protein Fam21." (PMID 29777037, 2018). "The discovery of a missense mutation, Vps35 p.D620N implicates retromer dysfunction in the pathogenesis of Parkinson’s disease (PD)." (PMID 30155515, 2018). "In contrast to previously reported cases and families carrying VPS35 mutations, our patient had parkinsonism resembling PSP." (PMID 27861377, 2016). "Dysfunction of VPS35/retromer is a risk factor for neurodegenerative disorders, including AD (Alzheimer’s disease) and PD (Parkinson’s disease)." (PMID 26521016, 2015). "define the primary molecular defect associated with the Parkinson disease-linked retromer VPS35(D620N) mutation and, by revealing effects on retromer-mediated endosome-to-TGN transport, provide new insight into retromer deregulation in this disease." (PMID 24980502, 2014). "Mutations of VPS35, a component of the retromer complex have been associated with late onset familial Parkinson’s disease." (PMID 25288323, 2014). "Recently, a specific mutation in the retromer component VPS35, VPS35(D620N), has linked retromer dysfunction to familial autosomal dominant and sporadic Parkinson disease." (PMID 24980502, 2014). "The first WES study of parkinsonism revealed the p.D620N mutation in VPS35 (the vacuolar sorting protein 35 gene) by sequencing affected cousin-pairs in autosomal dominant kindreds with late-onset disease." (PMID 25061481, 2014).
Parkinson disease (continued). "Recently, using exome sequencing, 2 groups have independently identified a single c.1858G>A mutation in VPS35 as the probable cause of Parkinson's disease in several kindreds." (PMID 22154191, 2012). "We conclude that the VPS35 c.1858G>A mutation is an uncommon cause of familial Parkinson's disease in our population." (PMID 22154191, 2012). "Background/Objectives: The retromer protein complex is involved in various physiological processes, especially endosomal trafficking, and its dysregulation has been linked to Alzheimer's disease and Parkinson's disease, as well as VPS35 knockout (KO), causing early embryonic lethality." (PMID 41751560, 2026). "Thus, a VPS35/LRRK2 axis linked to dominant Parkinson's disease intersects with a pathway mediated by proteins encoded by the recessive Parkinson's disease genes." (PMID 41164908, 2025). "Variants in seven genes (LRRK2, GBA1, PRKN, SNCA, PINK1, PARK7 and VPS35) have been formally adjudicated as causal contributors to Parkinson’s disease; however, individuals with Parkinson’s disease are often unaware of their genetic status since clinical testing is infrequently offered." (PMID 39074992, 2024). "Interestingly, altered ATG9A localisation can be caused by the Parkinson’s disease–associated VPS35 mutation D620N, which also impairs autophagy." (PMID 36446521, 2023). "A missense mutation (D620N) in VPS35 leads to autosomal-dominant, late-onset Parkinson’s disease." (PMID 34530877, 2021). "It has been reported that additional monogenic forms of Parkinson’s may interplay with the PINK1/Parkin pathway including the Asp620Asn (D620N) mutation of the retromer-associated VPS35 gene." (PMID 34767452, 2021). "Parkinson's causing D620N autosomal dominant mutation in the VPS35, the cargo binding subunit of the retromer complex also elevates LRRK2 mediated Rab protein phosphorylation through an unknown mechanism." (PMID 33367571, 2021). "Finally, we obtained neutrophils form three Parkinson's patients with VPS35[D620N] mutations and three healthy control donors." (PMID 33367571, 2021). "Mutant (D620N) VPS35-induced loss of SNpc DAergic neurons and impaired DAergic neurotransmission in the ST is expected to cause motor dysfunction, and resulting parkinsonism behavioral phenotypes, including hypokinesia and bradykinesia, of heterozygous VPS35D620N/+ mice." (PMID 33257649, 2020). "Furthermore, LRRK2-mediated Rab10 phosphorylation is increased in neutrophils as well as monocytes isolated from three Parkinson's patients with a heterozygous VPS35[D620N] mutation compared with healthy donors and idiopathic Parkinson's patients." (PMID 29743203, 2018). "Drosophila models of vacuolar protein sorting 35 (VPS35)-associated Parkinson’s disease." (PMID 29686647, 2018). "A mutation in the VPS35 gene has been associated with Parkinson's disease." (PMID 27148354, 2016). "In mice-models for Parkinson's disease, a VPS35 deficiency could contribute to retinal ganglion neuro-degeneration, leading to the blindness of many retinal degenerative disorders." (PMID 27148354, 2016). "In addition, mutations in the endo-lysosomal trafficking machinery have been implicated in neurodegenerative disorders including ALS and FTD (CHMP2B, FIG4, VAPB, and VCP) and defects in retrograde trafficking increase the risk for Parkinson's disease (VPS35)." (PMID 26357016, 2015). "We have employed this method to GFP tag OCRL (a phosphoinositide-5-phosphatase in the endocytic pathway) and Vps35 (a Parkinson's disease-implicated component of the endosomal retromer complex) in diverse Drosophila tissues including neurons, glia, muscles and hemocytes." (PMID 26700726, 2015). "Parkinson’s disease can be caused by a rare mutation in the protein VPS35, but the mechanism responsible for this is largely unknown." (PMID 24819384, 2014). "Mutations in Vps35 have been associated with the development of Parkinson’s disease." (PMID 24886063, 2014).